EGR4 (early growth response 4)
Diseases named in the same sentence as EGR4 in open-access papers:
EGR4 is named in the same sentence as 49 diseases in open-access papers, as found by Europe PMC text mining. Sharing a sentence is not in itself a finding about the gene and the disease. The quoted sentences say what the papers report.
breast carcinoma (5 papers, 2015 to 2025). "The results showed that EGR4 was expressed in most of the breast cancer cell lines from different sub-types." (PMID 35326716, 2022). "The results demonstrated that, except EGR4, the other EGRs were differentially expressed genes in breast cancer." (PMID 33614706, 2020). "As indicated by the results, the transcriptional levels of EGR1, EGR2, and EGR3 were significantly reduced in patients with BRCA (p < 0.05), whereas the expression level of EGR4 was very low in both breast cancer and normal breast tissues." (PMID 33614706, 2020). "Given that HSF1 plays a role in cancer progression, metastasis, and drug resistance, and our previous finding that EGR4 is regulated by HSF1 in breast cancer cells, the aim of this study was to more fully investigate the potential oncogene EGR4 and its regulation by HSF1." (PMID 35326716, 2022). "We next examined EGR4 protein levels in a panel of human breast cancer cell lines by Western blot." (PMID 35326716, 2022). "The EGR family members, except EGR4, were all genes with differential expressions in breast cancer." (PMID 33614706, 2020). "Previous research on EGR4 in cancer suggests it may be connected to advanced tumourigenesis, with a role in the cell proliferation and bone metastasis of small cell lung cancer, as well as an upregulated expression correlating with the breast cancer grade." (PMID 35326716, 2022). "Since we had observed the inverse association between HSF1 and EGR4-S in HER2+ cancer cells across several experimental conditions, we decided to examine the effect of directly manipulating EGR4 and HSF1 levels on breast cancer cells." (PMID 35326716, 2022). "In conclusion, the results here suggested that, except EGR4, higher levels of other EGR family members indicated better OS and DFS in breast cancer." (PMID 33614706, 2020). "Other regulators of ME1 expression include the canonical Wnt signaling pathway in breast cancer, dietary factors such as a high-fat diet in intestinal and hepatic tissues, and signaling through peroxisome proliferator-activated receptor (PPAR)/early growth response protein 4 (EGR4)." (PMID 39996805, 2025). "Hence, in some way, EGR4 can be regarded as a nonexpressing gene in both breast cancer and benign counterparts." (PMID 33614706, 2020). "EGR4 can be regarded as a nonexpressing gene in breast cancer, suggesting that it might be neither promoter nor suppressor of breast cancer." (PMID 33614706, 2020). "In fact, the DNB method reveals the existence of the pre-transition state, which, however, may not be detected by molecules such as EGR4, FOSL-1, FHL2, and DIPA, although these four transcription factors are proved to be effective for indicating the differentiation of breast cancer cells." (PMID 26284108, 2015).
epilepsy (4 papers, 2016 to 2023). A brain disorder characterized by episodes of abnormally increased neuronal discharge resulting in transient episodes of sensory or motor neurological dysfunction, or psychic dysfunction. "It was previously shown that multiple IEGs, including Egr1, Egr4, c-Fos, c-Jun, Naps4, Nur77, and Arc were upregulated in in vivo animal (from rodents to primates) and in in vitro models of epilepsy, as was confirmed in our study." (PMID 37234916, 2023).
male infertility (4 papers, 2014 to 2019). The inability of the male to effect fertilization of an ovum after a specified period of unprotected intercourse. "Nevertheless, further studies are required to validate whether these variants affect EGR4 gene function and increase the risk of male infertility associated with other genetic changes, such as EGR1 mutations." (PMID 28464846, 2017). "It has been reported that EGR4-null mice have male infertility because of arrested spermatogenesis but no female infertility is observed, suggesting that EGR4 plays a critical role in some types of human idiopathic male infertility." (PMID 25411851, 2014). "To date, this study is the first to screen the EGR4 gene in relation to male infertility." (PMID 28464846, 2017). "SAMD5 is the target of EGR4, which has a well-established role in male infertility but no female infertility due to the arrested spermatogenesis." (PMID 34968233, 2019).
small cell lung carcinoma (4 papers, 2014 to 2023). Small cell lung cancer (SCLC) is a highly aggressive malignant neoplasm, accounting for 10-15% of lung cancer cases, characterized byrapid growth, and early metastasis. "For example, the second most downregulated candidate, SYNPO, coding for synaptopodin, has been discovered to be a transcriptional target of early growth response factor 4 (EGR4) and to contribute to the growth of small cell lung cancer." (PMID 37803350, 2023). "The zinc finger transcription factor EGR4 has previously been identified as having a critical role in the proliferation of small cell lung cancer." (PMID 35326716, 2022). "EGR4 is known to play an important role in the proliferation of small cell lung cancer." (PMID 35326716, 2022).
cholangiocarcinoma (3 papers, 2020 to 2022). A carcinoma that arises from the intrahepatic biliary tree (intrahepatic cholangiocarcinoma) or from the junction, or adjacent to the junction, of the right and left hepatic ducts (hilar cholangiocarcinoma). "EGR4 is abundantly expressed in cholangiocarcinoma tissue and the low expression of EGR4 retards cell growth of cholangiocarcinoma." (PMID 34178038, 2021). "Few researches reported EGR4 in malignant tumors; only some articles reported that EGR4 might promote NSCLC, small cell lung cancer (SCLC), and cholangiocarcinoma (CHOL) to develop." (PMID 33614706, 2020).
schizophrenia (3 papers, 2012 to 2025). A major psychotic disorder characterized by abnormalities in the perception or expression of reality. "Other interesting genes, EGR3 and EGR4, both upregulated in response to neuronal activity, are central to schizophrenia risk pathways." (PMID 40719049, 2025). "Despite the correlation with age (Spearman's rho = −0.454; p = 0.001), EGR4 expression remained significantly associated with schizophrenia when age was used as a covariate (ANCOVA)." (PMID 22558445, 2012). "EGR3 interacts in regulatory feedback loops with other EGR-family genes in the immune system, including EGR1, EGR2, EGR4 and NAB2, each of which maps to GWAS loci for schizophrenia." (PMID 35941129, 2022).
gastric cancer (2 papers, 2023 to 2025). A primary or metastatic malignant neoplasm involving the stomach. "To further validate the effect of EGR4+ GC cells on eCAFs activation, we co-cultured control and EGR4-overexpressing GC cells with human primary gastric cancer-associated fibroblasts for 24 hours." (PMID 41203604, 2025). "In addition, TIMER2.0 data analysis showed that high expression of GDF15 or EGR4+GDF15+ and increased CAFs infiltration in gastric cancer patients had a significantly shorter survival time." (PMID 41203604, 2025).
lung cancer (2 papers, 2014 to 2019). A malignant neoplasm involving the lung. "Although the precise function of these genes in lung carcinogenesis remains largely unknown, our findings suggest that EGR4 may be a pivotal regulator that selectively activates the transcription of several target genes in lung cancer cells." (PMID 25411851, 2014).
breast tumours (1 paper, 2022). "Analysis of EGR4 exon expression across the TCGA BRCA RNA-seq dataset (n = 1085) found EGR4 exon 2 to be expressed at relatively comparable levels across breast tumours of different subtypes, with the median expression of exon 2 being higher than exon 1 for each subtype." (PMID 35326716, 2022). "Following this, we examined whether EGR4 could be readily detected by immunohistochemical (IHC) staining in human (HER2+) breast tumours." (PMID 35326716, 2022).
Cerebral ischemia (1 paper, 2018). Restriction of arterial blood supply to the brain associated with insufficient oxygenation to support the metabolic requirements of the tissue. "EGR4 is an important TF in neuronal maturation and its expression is induced by cerebral ischemia and inflammation." (PMID 29945546, 2018).
colon adenocarcinoma (1 paper, 2020). "EGR4 was a DEG in colon adenocarcinoma (COAD), glioblastoma multiforme (GBM), etc.." (PMID 33614706, 2020).
Cryptozoospermia (1 paper, 2023). A type of oligozoospermia in which spermatozoa can be detected in an ejaculate only after centrifugation and inspection of the pellet. "More importantly, an enhanced and prolonged expression of EGR4 was noticed in SPGs (also resembled the SSC-1 cells in Sohni's study 67), which could act as a transcriptional factor and inhibit the expression of UTF1 in part of SPGs from cryptozoospermia patients." (PMID 37151874, 2023).
depressive disorder (1 paper, 2021). A melancholy feeling of sadness and despair. "Its homolog Egr4 has not been studied in the context of reward processing, but it shows differential expression in addiction, depressive disorders and neurodegenerative diseases." (PMID 35082702, 2021).
Granuloma (1 paper, 2025). A compact, organized collection of mature mononuclear phagocytes, which may be but is not necessarily accompanied by accessory features such as necrosis. "The analysis of the images showed that EGR4 expression was higher in animals with focal and multifocal PTB-associated lesions, with no EGR4-positive cells observed in granulomas." (PMID 40218405, 2025). "In the apical mucosa, EGR4-positive cells formed part of epithelium and were scattered in the lamina propria without being part of granulomas." (PMID 40218405, 2025). "EGR4-expressing cells were identified as enterocytes, lymphocytes, macrophages, argentaffin cells, and goblet cells, mostly in the tissue surrounding the granuloma, but not as part of the granuloma." (PMID 40218405, 2025). "The EGR4-positive cells were mainly found in the cortex without being part of granulomas, surrounding lymphoid follicles, and sometimes in the proximities of the germinal centre." (PMID 40218405, 2025).
impaired spermatogenesis (1 paper, 2017). "In this study, we examined whether EGR4 variants are present in Korean men with impaired spermatogenesis." (PMID 28464846, 2017). "We identified eight variants in the EGR4 gene of Korean males with impaired spermatogenesis." (PMID 28464846, 2017).
ischemia (1 paper, 2024). A hypoperfusion of the BLOOD through an organ or tissue caused by a PATHOLOGIC CONSTRICTION or obstruction of its BLOOD VESSELS, or an absence of BLOOD CIRCULATION. "Mengozzi discovered that EGR2 and EGR4 were upregulated by neuroprotective erythropoietin in a model of middle cerebral artery occlusion, and this regulation was validated in stroke-related experiments, highlighting their association with ischemia." (PMID 38166990, 2024).
ischemic stroke (1 paper, 2024). A stroke disorder caused by obstruction of blood flow to the brain, due to thrombotic (local blood clot formation) or embolic (due to a blood clot or other material traveling from another site) event. "Egr4 provides neuroprotection in ischemic stroke by modulating the JNK signaling pathway, as outlined in a recent publication." (PMID 39126078, 2024).
lung adenocarcinoma (1 paper, 2014). A carcinoma that arises from the lung and is characterized by the presence of malignant glandular epithelial cells. "In addition, analysis of publicly available RNAseq data sets from The Cancer Genome Atlas (TCGA) revealed that EGR4 was up-regulated (more than 2-fold) in 17 of 39 lung adenocarcinoma cases, and in 19 of 46 squamous cell carcinoma (SCC) cases compared with their corresponding normal lung." (PMID 25411851, 2014).
retinal degeneration (1 paper, 2021). Degeneration of the retina. "In the group of slow adapters, we identified several downregulated genes that are involved in the development and/or progression of retinal degeneration (Cebpb, Egr4, and Ier5l) or apoptosis (Nrtn, Ccdc85b, Junb and Jund)." (PMID 34404875, 2021).
status epilepticus (1 paper, 2016). Status epilepticus is defined as a continuous seizure lasting more than 30 min, or two or more seizures without full recovery of consciousness between any of them. "Kainic acid induces recurrent seizures, and the selected time point (i.e., 6 h) after the induction of status epilepticus enabled us to observe not only late-response genes but also early-response genes (e.g., Fos, JunB, FosB, Egr2, Egr4)." (PMID 25636686, 2016).
viral infection (1 paper, 2023). "The induction of EGR1 following viral infection stimulates multiple inflammatory factors (EGR2 and EGR4) and mediates host cell response to viruses." (PMID 37998351, 2023).
cancer (9 papers, 2019 to 2025). A tumor composed of atypical neoplastic, often pleomorphic cells that invade other tissues. "In this study, we employed scRNA-seq to analyze the metastatic lymph nodes and paired primary tumors from GC patients, leading to the identification of an EGR4+ cancer cell subpopulation strongly associated with GC metastasis." (PMID 41203604, 2025). "Furthermore, CellChat analysis identified robust interactions between EGR4+ GC cells and cancer-associated fibroblasts (CAFs), particularly extracellular matrix (ECM)-remodeling eCAFs." (PMID 41203604, 2025). "Therefore, we analyzed scRNA-seq data of GC tissues and paired metastatic lymph nodes to investigate genes involved in GC metastasis, and identified the enrichment of EGR4+ cancer cells associated with poor prognosis in metastases." (PMID 41203604, 2025). "Moreover, EGR4 has been detected in low levels in mammary epithelial cells of different species, as well as in colorectal cancer-associated fibroblasts, among other tissues, even being related to the proliferation of cancer cells." (PMID 40218405, 2025). "Functioning as a transcription factor, EGR4 regulates the expression of various targeted genes and plays diverse roles in various cancers." (PMID 41203604, 2025). "Among the H3K27me3-marked genes activated by CTX treatment, Egr4 and Klf4 were both transcription factors extensively studied in cancers." (PMID 37963880, 2023). "Consistent with our earlier finding that EGR4 expression is upregulated in Ras-transformed mammary cells, EGR4 was highly expressed in cancer cells from the HER2+ subtype, which typically exhibit Ras pathway activation." (PMID 35326716, 2022). "The full significance of this finding will likely become apparent with the further characterisation of EGR4 and EGR4-S functions in cancer." (PMID 35326716, 2022). "The biological function and molecular processes of EGR4 in cancers was still rarely discovered." (PMID 34178038, 2021). "Additionally, several motifs were found to be specifically disrupted in certain cancer types, such as M2321_1.02 (TP63) in Bone-Osteosarc, M6446_1.02 (RARG) in Breast-AdenoCA, and M5371_1.02 (EGR4) in Lymph-CLL." (PMID 37782656, 2023). "Early growth response protein 4 (Egr4), a transcription factor belonging to the EGR family of zinc-finger transcription factors, is reportedly involved in the regulation of cell growth and apoptosis in cancers." (PMID 37963880, 2023).
tumor (8 papers, 2017 to 2025). "More importantly, in nude mice tail vein-lung metastasis model, we found that EGR4 overexpression significantly enhanced tumor cell colonization in the lungs." (PMID 41203604, 2025). "Concurrently depleting ZNF205‐AS1 and EGR4 more significantly repressed NSCLC tumour growth in vivo." (PMID 30556283, 2019). "EGR4 could also be readily detected by Western blot analysis of tumour lysates derived from HER2+ patient tumours." (PMID 35326716, 2022). "In other tumour contexts, EGR4 has also been connected to advanced tumourigenesis." (PMID 35326716, 2022). "The concurrent knockdown of ZNF205‐AS1 and EGR4 more significantly repressed tumour growth." (PMID 30556283, 2019). "Apoptosis marker TUNEL staining of subcutaneous xenografts displayed that ZNF205‐AS1 or EGR4 knockdown both promoted cell apoptosis of subcutaneous tumours, and concurrent knockdown of ZNF205‐AS1 and EGR4 more significantly promoted cell apoptosis of subcutaneous tumours." (PMID 30556283, 2019). "However, downregulation of EGR4 inhibits cholangiocarcinoma tumor cell growth." (PMID 41203604, 2025). "Gain‐of‐function and loss‐of‐function assays demonstrated that both ZNF205‐AS1 and EGR4 promoted NSCLC cell growth in vitro and NSCLC tumour growth in vivo." (PMID 30556283, 2019). "Functional assays revealed that consistent with ZNF205‐AS1, EGR4 also promoted NSCLC cell growth in vitro, and NSCLC tumour growth in vivo." (PMID 30556283, 2019). "In non-small cell lung cancer, EGR4 promotes tumor growth through interacting with long non-coding RNA ZNF205-AS1 in a positive feedback manner." (PMID 41203604, 2025). "We showed that the expression of EGR1, EGR2, EGR3, and EGR4 was significantly lowered in HCC specimens in comparison to nontumor specimens, which suggested that members of the EGR family may serve as a tumor suppressor in the progression of HCC." (PMID 36046377, 2022). "IHC staining for HER2, HSF1, and EGR4 in tumour punch biopsies revealed the positive nuclear staining of HSF1 and EGR4 in tumours presenting with positive membrane staining for HER2 across 15 tumour samples." (PMID 35326716, 2022). "However, a large number of genes considered as oncogenes or that promote tumour growth and/or metastasis, such as SKI, EGR4, SNAI1 and CEMIP2, were also overexpressed in response to TPL." (PMID 32543350, 2020). "Collectively, these results suggested that targeting the positive feedback loop between ZNF205‐AS1 and EGR4 inhibited NSCLC tumour growth in vivo, but did not regulate senescence." (PMID 30556283, 2019).
infection (3 papers, 2013 to 2025). The state of being infected such as from the introduction of a foreign agent such as serum, vaccine, antigenic substance or organism. "We found that 172 transcripts were differentially expressed in response to T. gondii infection of villous explants, with 22 of these transcripts also being differentially expressed in response to infection of PHT cells, which included EGR3, EGR4, and CCL22." (PMID 29317509, 2018). "Animals with diffuse lesions and low levels of EGR4-expressing cells were not able to contain the infection effectively; they developed clinical signs and were sacrificed earlier (5.92 ± 1.86)." (PMID 40218405, 2025).
EGR4 also shares sentences with these, for which no sentence is quoted: female infertility (2 papers); ankylosing spondylitis (1); Anxiety (1); astrocytoma (1); colon cancer (1); cryptorchidism (1); deafness (1); diabetic retinopathy (1); esophageal tumor (1); glioblastoma multiforme (1); hepatocellular carcinoma (1); Hyperammonemia (1); Infertility (1); melanoma (1); myopathy (1); myositis (1); neurodegenerative disease (1); Neurological Disease (1); non-small cell lung carcinoma (1); prostate carcinoma (1); psychosis (1); squamous cell carcinoma (1); Stroke (1); triple-negative breast carcinoma (1); tuberculosis (1).